IRF8 (interferon regulatory factor 8)
Diseases named in the same sentence as IRF8 in open-access papers (continued):
Sharing a sentence is not in itself a finding about the gene and the disease.
lung adenocarcinoma (5 papers, 2016 to 2026). A carcinoma that arises from the lung and is characterized by the presence of malignant glandular epithelial cells. "In addition to its role in AML, elevated IRF8 expression is associated with poor survival in lung adenocarcinoma, according to an analysis of TCGA data." (PMID 41596598, 2026). "IRF8 deficiency impaired the normal development of myeloid cells and induced the differentiation of myeloid cells toward MDSCs, thereby accelerating the immune escape of lung adenocarcinoma cells." (PMID 39049031, 2024). "Hopefully, our single-cell pseudotemporal analysis showed that IRF8 was rapidly down-regulated and maintained at a long-term low level as MDSC developed and matured, and IRF8 was also down-regulated in lung adenocarcinomas." (PMID 39049031, 2024). "The 5 lung adenocarcinoma cohorts were, respectively simulated as high and low IRF8 expression groups with the upper and lower quartiles as the cut-off points." (PMID 39049031, 2024). "IRF8 promotes MDSC formation in lung adenocarcinoma which lacks experimental verification, especially since IRF8 regulates MDSC differentiation through the IL6-JAK-STAT3 pathway, which only provides us with theoretical insights." (PMID 39049031, 2024). "In the GSE41271, GSE42127, and TCGA cohorts, multivariate Cox analysis confirmed that high expression of IRF8 is a protective independent prognostic factor for lung adenocarcinoma." (PMID 39049031, 2024). "The expression of IRF8 is closely related to the development of MDSCs in the tumor microenvironment of lung adenocarcinoma." (PMID 39049031, 2024). "Analysis of TCGA indicates that high STING and IRF8 expression levels are significantly correlated with the beneficial prognosis of cancer patients, such as lung adenocarcinoma, liver cancer and sarcoma." (PMID 35973990, 2022). "IRF8 is an independent prognostic factor for lung adenocarcinoma." (PMID 39049031, 2024). "In addition, our study showed that high expression of IRF8 was an independent protective factor for lung adenocarcinoma." (PMID 39049031, 2024). "Therefore, we explored the practical clinical significance of variations in the expression of IRF8 in lung adenocarcinoma patients." (PMID 39049031, 2024). "Targeting the activation of IRF8 may be a new immunotherapy strategy for lung adenocarcinoma." (PMID 39049031, 2024). "Therefore, we inferred that downregulation of IRF8 might induce MDSC formation by activating the IL6-JAK-STAT3 pathway in lung adenocarcinoma." (PMID 39049031, 2024). "Therefore, we suggest that targeting the activation of IRF8 to inhibit the differentiation of MDSCs may provide a new approach for immunizing lung adenocarcinoma." (PMID 39049031, 2024). "Therefore, activating IRF8 may be another interesting targeted approach for the immunotherapy of lung adenocarcinoma." (PMID 39049031, 2024). "Therefore, we speculate that IRF8 may affect MDSC differentiation by regulating the IL6-JAK-STAT3 pathway in lung adenocarcinoma." (PMID 39049031, 2024). "In both the GSE41271 and TCGA lung adenocarcinoma cohorts, the IL6-JAK-STAT3 pathway was activated in the MDSC high infiltration group, while the IL6-JAK-STAT3 pathway was inhibited in the IRF8 high-expression group." (PMID 39049031, 2024). "The 5 lung adenocarcinoma cohorts were divided into high- and low-MDSC infiltration groups and high- and low-IRF8 expression groups, respectively, with the upper and lower quartiles as the cut-off points." (PMID 39049031, 2024). "The results showed that IRF8, RASSF2, and EVI2B were significantly downregulated in lung adenocarcinoma tumors." (PMID 39049031, 2024). "We further investigated the expression of IRF8, CD4, RASSF2, and EVI2B in myeloid subtypes of lung adenocarcinoma." (PMID 39049031, 2024). "Analysis of the Cancer Genome Atlas (TCGA) revealed that high IRF8 and STING levels were significantly correlated with the beneficial prognosis of cancer patients, such as lung adenocarcinoma, liver cancer and sarcoma." (PMID 35973990, 2022).
lung adenocarcinoma (continued). "Our study showed that IRF8 expression was high in the early stages of MDSC development but rapidly decreased with cell development and maintained a low expression state for a long time in lung adenocarcinoma." (PMID 39049031, 2024). "In addition, we found a significant inverse correlation between IRF8 expression and MDSC infiltration in the lung adenocarcinoma TME." (PMID 39049031, 2024).
periodontitis (5 papers, 2015 to 2025). An acute or chronic inflammatory process that affects the tissues that surround and support the teeth. "In the context, we suggested that CTSS might play an essential role in bone loss involved in periodontitis progression by interacting with IRF8." (PMID 26334995, 2015). "Periodontitis induced the development of GMPs toward the neutrophil lineage at the expense of monocytic differentiation, as indicated by the dynamic changes in monocytic signature genes (F13a1, Irf8, and Ly86) and neutrophil-associated genes (Camk1d, S100a8, and S100a9) along the trajectory." (PMID 40521205, 2025). "Therefore, we speculated that PLEK might contribute to the periodontitis progression via interacting with IRF-8." (PMID 26334995, 2015). "In conclusion, this study identified several genes (CTSS, PLEK, IRF-8, PTGS2 and FOSB) that involved in the development and progression of periodontitis." (PMID 26334995, 2015). "Our in vitro data align with this, showing IFN-γ pathway activation (IRF8, STAT1, IL-1β) during macrophage polarization under P. gingivalis infection, suggesting a positive link between RANKL and IFN-γ in regulating osteoclast differentiation in periodontitis." (PMID 39595193, 2024). "This study identified genes (CTSS, PLEK, IRF-8, PTGS2, and FOSB) that may be involved in the development and progression of periodontitis." (PMID 26334995, 2015).
primary immunodeficiency (5 papers, 2013 to 2023). "The loss of IRF8 expression due to mutations leads to primary immunodeficiency, which is characterized by life-threatening respiratory infections in childhood." (PMID 37508555, 2023). "Recently, a genetic approach revealed that heritable mutations in IRF-8 gene determine human primary immunodeficiency, which affects the functional activity of DC, resulting detrimental in anti-mycobacterial immune response." (PMID 23717393, 2013). "Though T cell immunity is clearly important for anti-mycobacterial defense, myeloid cells are also essential, as demonstrated by many forms of primary immunodeficiency such as GATA2 haploinsufficiency, IFNGR1/2 deficiency, Chronic granulomatous disease, and IRF8 deficiency." (PMID 30984189, 2019).
uveitis (5 papers, 2016 to 2022). An inflammatory process affecting a part of or the entire uvea. "The observation that ocular BD is associated with an aberrant IRF8 status supports the role of this factor in the pathogenesis of this particular uveitis entity." (PMID 28881647, 2017). "Of the tested elements, only IRF8 was shown to be associated with susceptibility to uveitis in BD patients, whereby functional studies showed that the risk gene was able to regulate IRF8 expression as well as IFN-γ and IL-10 production." (PMID 26794091, 2016). "A previous study observed that loss of interferon regulatory factor 8 (IRF8) in retinal microglial cells and neurons protected the mice from the development of uveitis (with fewer numbers of inflammatory cells in the vitreous and less retinal infolding)." (PMID 35565057, 2022). "However, whether IRF8 is associated with uveitis is poorly studied." (PMID 28432342, 2017). "We carried out a two-stage case control study to investigate the association of 13 SNPs of TRIM20, IRF3, IRF7, IRF8, MYD88 and NF-κB1 in two different uveitis entities." (PMID 26794091, 2016). "We focused on these drugs although other agents that are often used in the treatment of clinical uveitis such as alkylating agents (cyclophosphamide etc.), antimetabolites (azathioprine, MTX) and anti-TNF antibody, may also have an effect on IRF8 methylation." (PMID 28432342, 2017). "It is also not clear whether our findings can be generalized to other uveitis entities, although preliminary findings from our group showed that IRF8 methylation abnormalities can also be found in patients with Vogt-Koyanagi-Harada uveitis (unpublished data)." (PMID 28881647, 2017).
asthma (4 papers, 2017 to 2023). "These two cytokines are critical for asthma development, and it might be interesting to know if IRF8 deficiency in Th9 cells has an impact on this atopic disease." (PMID 29233972, 2017). "We observed a third cluster which expressed Irf8 in the lungs of mice subjected to either asthma or tolerance protocol." (PMID 37251386, 2023). "Also, in the lungs of animals treated with allergen in order to induce either experimental asthma or tolerance, we found an additional cDC population (Cluster 6) which expressed Irf8, Batf3 as well as low levels of Irf4, Sirpa and Itgam." (PMID 37251386, 2023).
B cell lymphomas (4 papers, 2013 to 2024). "We concluded that in B cell lymphoma models, IRF8 KO and/or expression of mutant variants decrease CD74 and HLA-DM expression, mainly deregulating intracellular antigen processing and loading, rather than MHCII expression on the cell surface." (PMID 38996030, 2024). "Here, we showed that B cell lymphomas carrying IRF8 gene mutations, missense or truncating, are better equipped to evade the immune system than those with IRF8 in a WT configuration." (PMID 38996030, 2024). "We modeled IRF8 variants in B cell lymphomas and found that they affected the expression of regulators of antigen presentation." (PMID 38996030, 2024). "Our in vivo model of IRF8-mutant B cell lymphoma validated this initial observation and linked it to defective antigen loading into MHCII complexes because it could be rescued with CD74 ectopic expression." (PMID 38996030, 2024). "We concluded that similarly to CIITA, EZH2, and CREBBP mutations, IRF8 variants may add to the pathogenesis of B cell lymphomas by impairing antigen presentation in the context of MHCII." (PMID 38996030, 2024). "On the basis of these previous reports we hypothesized that IRF8 may function as a tumor suppressor in EBV associated B-cell lymphomas." (PMID 23658517, 2013). "However, in these two instances, IRF8 is either mutated in the germ line or specifically deleted in developing NK cells, thus not fully recapitulating our model (or primary DLBCLs), wherein only the B cell lymphoma cell is IRF8 mutant." (PMID 38996030, 2024). "In agreement with this postulate, in an unbiased CRISPR screen in DLBCL cell lines, IRF8 was identified as an “essential oncogene”, and we found the IRF8 deletion abolishes B cell lymphoma growth in vivo." (PMID 38996030, 2024). "In agreement with the mouse B cell lymphoma models, IRF8-mutant DLBCLs displayed significantly diminished signatures of NK cell infiltrate as well as selected CD4 subpopulations, including TH1, but not TH2." (PMID 38996030, 2024). "Our in vitro data suggested that expression of mutant IRF8 in B cell lymphomas deregulates antigen processing/loading and ultimately presentation in an MHCII context thus eliciting a subpar CD4 response." (PMID 38996030, 2024). "Also, the IRF8-mutant models that we examined in vitro and in vivo are monoallelic, and it is possible that the presence of the WT allele may uncover further aspects of the IRF8 role in B cell lymphomas." (PMID 38996030, 2024). "We concluded that in murine models of B cell lymphomas examined in vitro, IRF8 regulates antigen OVA-driven T cell activation in the context of MHCII but not MHCI." (PMID 38996030, 2024). "This profile partially recapitulates the microenvironment remodeling detected in the mouse model of IRF8 WT or mutant B cell lymphoma that we developed." (PMID 38996030, 2024). "A recent report showed that IRF8 expression in tumor-associated macrophages (TAMs) promoted T cell exhaustion and that, in agreement with our findings in B cell lymphoma models, IRF8 was required for TAMs to properly present cancer cell antigens." (PMID 38996030, 2024). "Last, we also detected a significant increase in TFH cells in the mouse models of IRF8-mutant B cell lymphoma, which was corrected by CD74 ectopic expression." (PMID 38996030, 2024). "We concluded that CD74 is an important mediator of IRF8 dysfunction in B cell lymphomas." (PMID 38996030, 2024). "Capitalizing on the isogenic models of B cell lymphomas expressing IRF8 WT, N87Y, and I424T that we developed, we then tested whether these IRF8 mutants lose their promoter binding capacity." (PMID 38996030, 2024). "Therefore, we decided to examine whether the IRF8 mutant–associated remodeling of the TME and attendant growth advantage that we detected in B cell lymphoma models, was still amenable to correction with checkpoint inhibitors of the PD-1/PD-L1 pathway." (PMID 38996030, 2024).
B cell lymphomas (continued). "Thus, in the context of IRF8-mutant B cell lymphoma, it is possible that still to be identified secreted factors may limit NK recruitment to the tumor milieu." (PMID 38996030, 2024). "The defective activation of CD4 (but not CD8) T cells by IRF8-mutant B cell lymphomas, together with the well-recognized role of MHCII deficiency in DLBCL biology, suggested that IRF8 variants may deregulate genes and processes that are involved in antigen loading/processing and/or presentation." (PMID 38996030, 2024). "In our model system, ectopic expression of CD74 was sufficient to rescue the immune and clinical phenotypes detected in IRF8-mutant B cell lymphomas, but it did not significantly change the immune landscape or growth pattern of IRF8 WT B cell lymphomas." (PMID 38996030, 2024). "In murine B cell lymphoma models, which allow for in vitro (CD4 DO-11.10 cells) and in vivo functional examination of defective antigen presentation, CD74 appear to be the main “target” of IRF8 effects." (PMID 38996030, 2024). "To test the idea that IRF8’s role in DLBCL biology may be related to a defective antigen processing/presentation, we first created IRF8 KO models in three murine B cell lymphoma cell lines—A20, 2PK-3, and BCL1." (PMID 38996030, 2024). "Expression of IRF8 mutants in murine B cell lymphomas suppressed CD4, but not CD8, activation elicited by antigen presentation and downmodulated CD74 and human leukocyte antigen (HLA) DM, intracellular regulators of antigen peptide processing/loading in the major histocompatibility complex (MHC) II." (PMID 38996030, 2024). "We note that an antibody that detects CLIP in mouse cells is not available, so these quantifications could not be extended to the IRF8-modified murine B cell lymphoma models." (PMID 38996030, 2024). "Last, to mitigate concerns that the ectopic expression of CD74 may enhance CD4 activation irrespective of IRF8 status, and to define whether CD74 can rescue the IRF8-mutant phenotype, we tested CD74 effects on B cell lymphoma models expressing IRF8 WT, the DBD mutant N87Y, or the CTD mutant I424T." (PMID 38996030, 2024). "In this way, we detected the induction of transcription factors genes implicated in B-cell differentiation and activation, PAX5 and IRF8 as well as of MYBL2, a transcription factor participating in cell cycle progression and recently described as a direct Notch1 target in B cell lymphomas." (PMID 31676012, 2019).
Behçet's disease (4 papers, 2016 to 2022). "Polymorphisms within or near the IRF8 gene were associated with susceptibility to EPF and other diseases such as MS, SLE, and SSc, as well as Behçet’s disease but not Vogt–Koyanagi–Harada syndrome." (PMID 35632621, 2022).
colorectal cancer (4 papers, 2019 to 2025). A primary or metastatic malignant neoplasm that affects the colon or rectum. "Under physiological conditions, the transcription factor IRF8 represses myeloid-derived SPP1 expression; however, in the murine colorectal cancer microenvironment, forced loss of IRF8 led to enhanced production of SPP1 by PMN-MDSCs and tumour cells." (PMID 33187209, 2020). "In comparison to normal colon tissue, human colorectal cancer tissues exhibit significantly elevated levels of DNMT1 and DNMT3b, reduced expression of IRF8, and increased DNA methylation at the IRF8 promoter." (PMID 41368628, 2025). "Studies of IRF8 mRNA levels in normal human colon and colorectal carcinoma (CRC) revealed that IRF8 is downregulated in tumor tissues as compared to non-malignant counterpart tissues." (PMID 33766090, 2021).
coronary heart disease (4 papers, 2016 to 2024). "Notably, gene variants in IRF8 have been identified as risk factors for coronary heart disease." (PMID 38012001, 2024).
Obesity (4 papers, 2021 to 2025). Accumulation of substantial excess body fat. "Furthermore, adeno-associated virus-mediated IRF8 knockdown in the mouse liver markedly alleviated hepatic steatosis and obesity-related metabolic syndrome." (PMID 40083324, 2025). "However, with obesity, we observed increased accessibility of genes involved in cell cycle regulation (ATM, CDKN1C, BCL2L11), autophagy (HSPA8, IRF8, PEX5), and protein catabolism (CDC34, CTSB, UBB)." (PMID 39872537, 2024). "Finally, motif analysis revealed that promoter regions open in monocytes from lean subjects at T3 (closed in monocytes from subjects with obesity) harbor binding sites for transcription factors PU.1 and AP-1 and interferon regulators IRF1, IRF3, and IRF8." (PMID 34195568, 2021).
osteosarcoma (4 papers, 2020 to 2022). A usually aggressive malignant bone-forming mesenchymal neoplasm, predominantly affecting adolescents and young adults. "While most research supports an anti-metastasis role for IRF8 in non-hematopoietic cancers, one study found that IRF8 promoted EMT-like phenomena, cell motility, and invasion in a human osteosarcoma cell line providing evidence for a possible role in the acquisition of a metastatic-like phenotype." (PMID 36078039, 2022).
renal cell carcinoma (4 papers, 2019 to 2023). "The IRF8 overexpression in TAMs decreases tumor mass and improves patient survival in renal cell carcinoma (RCC)." (PMID 37380989, 2023). "While IRF8 increases tumor suppressor genes, one study also showed an IRF8-induced decrease in oncogene (Yap1 and Survivin) expression in renal cell carcinoma cell lines." (PMID 36078039, 2022). "Similarly, in gastric, nasopharyngeal, esophageal, colorectal, lung, prostate, and renal cell carcinomas the expression of IRF8 is downregulated." (PMID 36078039, 2022).
Sepsis (4 papers, 2016 to 2025). Sepsis is defined as life-threatening organ dysfunction caused by a dysregulated host response to infection. "The final section highlights the need for multi-centre validation, further elucidating the causal hierarchy of IRF8, and conducting windowed clinical trials to advance the model’s application in precision treatment for sepsis." (PMID 40861459, 2025). "The down-regulation of interferon regulatory factor 8 (IRF8) in sepsis patients and ARDS patients promoted inflammatory and infection and activated macrophages through IFN-γ." (PMID 37443002, 2023). "A six-gene panel including EOMES, LTF, CSF1R, HLA-DRA, IRF8 and MPEG1 was discovered and validated with a high accuracy both in sepsis subjects and sepsis-induced ARDS subjects." (PMID 37443002, 2023). "Four genes of them were differential expressed among sepsis-alone group, sepsis-induced ARDS group and controls, which were CSF1R, HLA-DRA, IRF8 and MPEG1." (PMID 37443002, 2023). "In sepsis, RELA, CEBPB, NFKBIA, STAT6, IRF8 and SPI1 were downregulated, with no significant change in NFKB1, JUN and GLI1." (PMID 39444551, 2024).